NFKB1 (nuclear factor kappa B subunit 1)
Diseases named in the same sentence as NFKB1 in open-access papers (continued):
Sharing a sentence is not in itself a finding about the gene and the disease.
ovarian carcinoma (continued). "Accordingly, further mechanistic investigations showed that LINC00494 recruited transcription factor NFκB1 to bind on the promoter region of FBXO32, which inhibited the transcription of FBXO32, while suppressing the progression and development of ovarian cancer." (PMID 33585183, 2020). "Neither angiogenesis nor the transcription factors E2F1, SP3 and NFκB1 were identified in the original analysis of the ovarian cancer data." (PMID 22548828, 2012). "However, due to the limited time and funding, we are not allowed to explore the respective roles of FBXO32 and NFκB1 in ovarian cancer, which will be further studied in our future research for better clinical application of LINC00494 knockdown." (PMID 33585183, 2020). "Topological analysis of the complete network also suggests cross-regulation of angiogenesis-specific genes through SP3, NFκB1 and E2F1 in the normal and ovarian cancer networks, and we hypothesize that deregulation of these angiogenic genes may be associated with oncogenesis." (PMID 22548828, 2012).
glioblastoma (552 papers, 2007 to 2026). The most malignant astrocytic tumor (WHO grade IV). "Based on the results of the PPI network and KEGG enrichment analysis, AKT1, HIF1A, CDH1, and NFKB1 were identified as vortioxetine targets that also regulate glioblastoma." (PMID 40312983, 2025). "Thereof, more detailed research is required to gain better insight into the exact role of NFKB1 in glioblastoma." (PMID 31261921, 2019). "These bioinformatics and computational analyses suggest that vortioxetine suppresses glioblastoma development by modulating the functions and activities of AKT1, HIF1A, CDH1, NFKB1, and associated signaling pathways, such as the Rap1, chemical carcinogenesis-ROS, and HIF-1 signaling pathways." (PMID 40312983, 2025).
COVID-19 (541 papers, 2020 to 2026). A disease caused by infection with severe acute respiratory syndrome coronavirus 2. "SARS-CoV-2 infection of Calu-3 cells induced activity of the inflammatory TF families (STATs, IRFs, and NFκB-1), whose signalling is associated with severe COVID-19 cases." (PMID 37747932, 2023). "We found a significant upregulation (11.3-fold higher) of NFKB1 in severe COVID-19 patients (7.73 [0.86-47.18]) compared to the control group (0.68 [0.20-1.89]), P = 0.0001." (PMID 40927375, 2025). "The expression levels of the anti-inflammatory gene NFKB1A, an inhibitor of the pro-inflammatory transcription factor NFKB1, were higher in severe COVID-19 patients (1.65 [0.14-4.29]) compared to the control group (0.98 [0.22-2.55])." (PMID 40927375, 2025). "NFKB1 shows almost the same expression pattern in AD patients, COVID-19 patients, and in NHBE and Calu-3 cells, highlighting the important role in both AD and COVID-19 progression." (PMID 38257800, 2024). "TNF and NFκB1 are involved in the cytokine storm and a hyperinflammatory state, and increased levels are indicative of severe COVID-19." (PMID 38991709, 2024). "A computer model identified potentially beneficial drugs for critically COVID-19 patients that act by inhibiting the tumor necrosis factor (TNF)-induced NFkB1 signaling pathway, which is inhibited by APC activity." (PMID 36560757, 2022). "Andrographolide can bind to TNF and NFkB1 proteins to block the NFkB1 signaling pathway of TNF-induced cytokine storm in COVID-19 patients." (PMID 36238575, 2022). "Fluoxetine, tiotropium, and andrographolide targeted NFKB1, suppressed inflammation, and reduced the cytokine storm in COVID-19 patients." (PMID 34975885, 2021). "IL6, CXCL8, EGFR, FOS, PIK3R1, and NFKB1 were identified as common targets from the common pathways between cancers and COVID-19 (signaling by interleukins, TLR signaling, TNF-α signaling via NF-kB)." (PMID 34067609, 2021). "Specifically, JUN and NFKB1 are significantly upregulated in male monocytes with severe COVID-19 compared to females (q < 2.0 × 10−16)." (PMID 34330889, 2021). "When we directly compared COVID-19 and influenza, NFKB1, NFKB2, and TNF were up-regulated in COVID-19, whereas STAT1, TLR4, and genes for immunoproteasome subunits were up-regulated in influenza." (PMID 32651212, 2020). "Additionally, we found other mediators of neutrophil recruitment, such as CXCL1, as well as NFKB1, which is important for innate immune response and inflammation activation, to be downregulated in COVID-19 (+) tissues." (PMID 38932146, 2024). "Here, we observed increased hepatic expression of F3, AGTR1, and NFKB1 in COVID-19 individuals." (PMID 36560757, 2022). "It is hypothesized that the NF-κB pathway is a potential target in severe COVID-19 cases, and the inhibition of nuclear translocation of NFKB1 could be a potential therapy." (PMID 34067609, 2021). "Furthermore, by targeting NFKB1, miR-9 regulates inflammatory pathways related to COVID-19 pathogenesis." (PMID 34975885, 2021). "Our study identified that drug molecule andrographolide, naturally present in a medicinal plant Andrographis paniculata, has the potential to bind with crucial proteins to block the TNF-induced NFkB1 signaling pathway responsible for cytokine storm in COVID-19 patients." (PMID 34248936, 2021). "Collectively, the data suggest that the active form of Vitamin D could prevent the translocation of NFkB1 to the nucleus and, consequently, inhibit the cytokine storm in COVID-19." (PMID 33362771, 2020). "There was some limited evidence of e-cigarette-induced IL6 and TNF downregulation, and NFκB1 upregulation, suggesting that vapers may be at a lower risk of developing severe COVID-19 versus smokers, but at increased risk versus nonsmokers." (PMID 38991709, 2024).
COVID-19 (continued). "For instance, while reducing the correlation between DEGs including IL10, CXCL8, NFKB1, ARG1, and SOD2, new strong associations appeared between ELANE, DEFA4, AZU1, CTSG, and LCN2, with an overall tendency to higher relationships amid neutrophil-mediated immunity genes in COVID-19 patients." (PMID 35269470, 2022). "Finally, we employed a structure-based molecular docking method to demonstrate that the andrographolide could bind with TNF and NFkB1, potentially blocking the TNF-mediated NFkB1 pathway underpinning cytokine storm in severe patients with COVID-19." (PMID 34248936, 2021). "NK cells from severe COVID-19 patients showed downregulation of HIF1A and GLUT1, and upregulation of NFKB1 (P < 0.05)." (PMID 40927375, 2025). "NFκB1 is a signalling molecule within the AGE-RAGE pathway and increased levels can be used as a prognostic indicator of severe COVID-19." (PMID 38991709, 2024). "A bioinformatics analysis of the single-cell and bulk RNA-seq profiling of COVID-19 patients’ data revealed a significant upregulation of cGAS-STING signalling pathway genes (TMEM173, IRF3, NFKB1, CGAS, IFNAR1, and TBK1) in the lung." (PMID 39459875, 2024). "Analysis of the transcription factors using the TRRUST database from our data (212 DEGs from GSE36854 and GSE21001) for MPXV infection and COVID-19 database by Metascape identified JUN, REL, STAT3, NFKB1, RELA, SP1, and so on." (PMID 37006463, 2023). "By constructing a protein-protein interaction (PPI) network, we ascertained FOS, NFKB1, NFKB1A, JUNB, and JUN as possible core target genes of quercetin for the treatment of COAD/COVID-19." (PMID 36249762, 2022). "We identified FOS, NFKB1, JUNB, JUN, and NFKB1A as core target genes of quercetin for the treatment of COAD/COVID-19." (PMID 36249762, 2022). "From 11 healthy cell-type TRNs and 8 COVID-19 cell-type TRNs, we identified 8 unique central TFs, FOXP1, RUNX1, FOS, SMAD3, JUN, NFKB1, PPARG, and STAT3." (PMID 35458567, 2022). "Conversely, liver samples from patients with COVID-19 presented a significant 1.9-fold increase in AGTR1, a 1.8-fold increase in NFKB1, and a 1.2-fold increase in F3 (p < 0.001)." (PMID 36560757, 2022). "A recent study about the genomics of COVID-19 showed that TFs like FOXC1, GATA2, YY1, FOXL1, and NFKB1 regulated the inflammatory network in SARS-CoV-2 infections." (PMID 35747501, 2022). "In contrast, many TFs were identified specifically as the top TFs in COVID-19 patients’ lung cell types, including SMAD3 in ciliated cells, NFKB1 and JUN in dendritic cells, PPARG in macrophage/monocyte cells, and STAT3 in T cells." (PMID 35458567, 2022). "In fact, when we compared the expression levels of the genes duplicated in NFKB1, RELA, and H3K36me3 in GSE152418 between the COVID-19 patients and healthy subjects, we observed a decrease in expression levels in the COVID-19 patients." (PMID 34456333, 2021). "NFKB1, NFKB2, IRF1, and CXCR3 were specifically up-regulated in COVID-19, and CXCL10, STAT1, TLR4, and genes for class II HLA and immunoproteasome subunits were specifically up-regulated in influenza." (PMID 32651212, 2020). "Additionally, some studies have identified cytokine signaling and upregulation of certain genes, such as NFKB1, and STAT1, in COVID-19-infected tissue." (PMID 38932146, 2024). "We then compared CD3+ cells isolated from COVID-19-infected subjects vs. healthy controls and found increased expression of activation markers including CD69, CD83, ICOS, RGS1 as well as other stress related genes including HIF1A, ATF4, NFKB1, and PR1." (PMID 36881624, 2023). "NF-kB signaling pathway genes (NFKBIA, NFKB1, RELA, NFKB2) were up-regulated in COVID-19 patients." (PMID 36380355, 2022). "Our study suggests that andrographolide could bind with TNF and NFkB1 proteins, block TNF-induced cytokine storm in COVID-19 patients, and warrant further experimental validation." (PMID 34248936, 2021).
COVID-19 (continued). "Furthermore, the downstream factors of TLR7 and BTK in TLR pathway, such as MYD88, IRF7, NFKB1, and JUN, and cytokines (TNF, IL1B, and IL18) were elevated in men with severe COVID-19." (PMID 34330889, 2021). "Both distinct and common biological functions were identified as illustrated by inflammatory response genes being highly active in both COVID-19 and influenza, but genes for transcription factors, including inflammatory factors (i.e., NFKB1/2, and STAT4) were up-regulated in COVID-19." (PMID 32651212, 2020). "FOS, JUN, NFKB1, JUNB, and NFKB1A had the highest degree values, so we concluded that these genes might be the core target genes of quercetin for the treatment of COAD/COVID-19." (PMID 36249762, 2022). "For instance, IL1B, NFKB1, NLRP3, PYCARD, and CASP1 are listed in the COVID-19 Disease Map, while there are molecules absent from it, including CCL3, 3L1, 4L2, CXCL1, 2, 3, 5, 16, TNFAIP6, C15orf48, TMEM176A/B, NFE2, PADI4, RAB20, ETS2, PHLDA2, FOLR3, and HP." (PMID 37719701, 2023).
asthma (538 papers, 2004 to 2026). "Previously NFκB1 deficiency was shown to inhibit Th2 cells and allergic inflammation in a Th2-dependent model of asthma, which involved percutaneous sensitization with an adjuvant." (PMID 37575259, 2023). "NFKB1 is the NF-κB p105 subunit, a typical inflammation pathway gene, and is associated with asthma." (PMID 35501805, 2022). "In the NFKB1, the A allele of rs35680095 (OR: 1.28; 95% CI 1.02–1.61) and the G allele of rs75071695 (OR: 3.25; 95% CI 1.19–8.87) were positively associated with asthma." (PMID 31168303, 2019). "Variants were found in NFKB1 (rs35680095 and rs75071695) elevating the risk of asthma and atopy development; furthermore, according to our results, all variants in this gene are involved in inactivation of miRNA." (PMID 31168303, 2019). "It was found that variants in NFKB1 have an important role in asthma according to studies that indicate enhanced NF-κB pathway activation in asthmatic tissues, and the NF-kB expression is increased in the airway epithelium of asthmatic humans." (PMID 31168303, 2019). "Interestingly, genetic score analyses demonstrated that combination variants in IL17RC and NFKB1 together increased the risk of asthma in comparison with the presence of these variants alone." (PMID 31168303, 2019). "The NFKB1 encodes a transcription factor that regulates inflammation and immune responses, and has been linked to a number of inflammatory diseases, such as autoimmune arthritis, asthma, and glomerulonephritis." (PMID 32038468, 2019). "Because of this potential dichotomous function, we examined the role of NFκB1 in the memory phase and the effector phase of trained immunity of ILC2s in a mouse model of asthma." (PMID 37575259, 2023). "To understand the role of NFκB1 in allergen-induced memory ILC mediated asthma, we treated C57B/6 mice with Alternaria (Alt) and saline (Sal)." (PMID 37575259, 2023). "We examined the role of NFkB1 in memory induction and memory-driven effector function in a mouse model of asthma." (PMID 37575259, 2023). "By searching PubMed, NFKB1, STAT6, E2F1, USF1, and CBFB were the verified asthma-related TFs, while NFKB1 and STAT6 were the newly discovered asthma-related genes in 2013." (PMID 24790987, 2014). "By detecting the RNA expression in buccal mucosa samples of patients with asthma, NFKB1 was found to be differentially expressed." (PMID 24790987, 2014). "The results suggested that Nfκb1 was important for the effector phase of memory ILC2-driven asthma." (PMID 37575259, 2023). "We speculate that NFκB1 positively regulated the effector phase of memory ILC2-induced asthma by heterodimerizing with RUNX1." (PMID 37575259, 2023). "NFκB1 was essential for the effector phase of memory-driven asthma." (PMID 37575259, 2023). "NFκB1 is important for the ILC2 mediated pathogenesis of allergen induced asthma." (PMID 37575259, 2023). "The role of NFκB1 in memory ILC2-mediated asthma is unknown." (PMID 37575259, 2023). "In conclusion, NFkB1 was essential for the effector phase of ILC2 memory and induction of memory-driven asthma in the mouse model." (PMID 37575259, 2023). "MiR-146-5p targets inflammatory mediators like COX2, IL-1β, KIT, NFKB1, TLR4, TRAF6, and UHRF1 and has been proposed as a predictor for asthma exacerbations in childhood asthma." (PMID 32998415, 2020). "NFKB1, STAT6, and E2F1 were the verified asthma-related TFs in PubMed, and they were discovered to exert regulatory impact in this study." (PMID 24790987, 2014). "NFκB1 was critical for IL33 production, ILC2 generation, and production of type-2 cytokines, which resulted in eosinophilic inflammation and other features of asthma." (PMID 37575259, 2023). "Preferential expression of NFκB1 and RUNX1 in ILC2s implied a non-canonical heterodimer-mediated execution of the ILC2 effector function in our asthma model." (PMID 37575259, 2023).
osteoarthritis (471 papers, 2009 to 2026). A noninflammatory degenerative joint disease occurring chiefly in older persons, characterized by degeneration of the articular cartilage, hypertrophy of bone at the margins and changes in the synovial membrane. "Of note, STAT3, RELA, and NFKB1 transcription factors identified are considered players in key pathogenic signaling pathways in osteoarthritis." (PMID 38938688, 2024). "Our results also highlighted that only three central genes—Prdx1, Nfkb1, and Bmp4—were differentially expressed during Mia-induced osteoarthritis, demonstrating a limited overlap in DEGs related to Mia-induced OA." (PMID 40722985, 2025). "Moreover, several transcription factors upstream of the stretch gene signature, identified by in silico analysis here (STAT3, RELA, and NFKB1), mediate osteoarthritis signaling pathways." (PMID 38938688, 2024).
lymphoma (460 papers, 2003 to 2026). A malignant (clonal) proliferation of B- lymphocytes or T- lymphocytes which involves the lymph nodes, bone marrow and/or extranodal sites. "DNA alkylation damage leads to increased lymphomas in Nfkb1−/− mice when compared with wild type mice." (PMID 30205516, 2018). "Despite the fact that our cohort is relatively small, we found oncologic manifestations in 29% of our cases (two thirds being lymphoma), suggesting that malignancies in patients with NFKB1 haploinsufficiency can occur more often than in unselected patients with CVID." (PMID 29477724, 2018).
psoriasis (458 papers, 2007 to 2026). An autoimmune condition characterized by red, well-delineated plaques with silvery scales that are usually on the extensor surfaces and scalp. "Other variants located at the chromosomal region where NFKB1 is found have been investigated and related to the risk of psoriasis, specifically rs1020760 and rs1609798." (PMID 34884808, 2021). "In reference to the main clinical outcomes, at least one NFKB1 variant has been associated with psoriasis severity." (PMID 31815120, 2019). "Previous studies have reported significant associations between common NFKB1 variants and psoriasis, including large-scale genome analysis involving thousands of patients and controls." (PMID 31815120, 2019). "Recently, genome-wide association studies (GWAS) have found a significant association between psoriasis and single-nucleotide polymorphisms (SNPs) within NFKB1, NFKBIA, and NFKBIZ." (PMID 31815120, 2019). "In particular, NFKB1 performs a crucial influence on keratinocytes in psoriasis by promoting Th1 and Th17 activation." (PMID 35889927, 2022). "We investigated the association between three common variants in NFKB1 (rs230526), NFKBIA (rs7152376), and NFKBIZ (rs3217713 indel) and the risk of developing psoriasis/PsA or their main clinical outcomes." (PMID 31815120, 2019). "Similarly, tissue levels of miR-9 are significantly reduced in psoriasis patients, suggesting a potential anti-inflammatory role for miR-9 through a feedback mechanism that downregulates NFKB1." (PMID 39796035, 2024). "Furthermore, NFKB1 (nuclear factor kappa B subunit 1) was shown to be elevated in psoriasis patients, exacerbating the symptoms of this condition." (PMID 35889927, 2022). "Additionally, overexpression of NFKB1 in psoriasis mice led to more pustules, an evident increase in acanthosis, as well as greater parakeratosis and desquamation." (PMID 35889927, 2022). "Overexpression of CHUK, IKBKB, NFKBIA, NFKB1, JAK2, STAT1 and STAT3, as inflammation related factors, was detected in the psoriasis model group." (PMID 34834106, 2021). "Oral administration of genistein in psoriasis patients for 8 weeks impaired the transcription of genes overexpressed in psoriasis, CXCL10, IL-6, STAT3, NFKB1, CCL4 while stimulated the transcription of gene repressed in psoriasis, IL-1RN in peripheral blood cells or lesional skin." (PMID 32751360, 2020).